MT-CO1 (mitochondrially encoded cytochrome c oxidase I)
Diseases named in the same sentence as MT-CO1 in open-access papers (continued):
Sharing a sentence is not in itself a finding about the gene and the disease.
progressive external ophthalmoplegia (1 paper, 2012). A mitochondrial myopathy characterized by slowly progressive paralysis of the levator palpebrae, orbicularis oculi, and extraocular muscles. "The gain of one cystein at 5895–5899, in the short non-coding region between the tRNA tyrosine and MT-CO1 genes, detected in cybrid H1, was described in one subject with progressive external ophthalmoplegia." (PMID 23300652, 2012).
infection (25 papers, 2012 to 2025). The state of being infected such as from the introduction of a foreign agent such as serum, vaccine, antigenic substance or organism. "Among the most significant differentially expressed genes, we noticed a downregulation of genes associated with cell death during infection, including FosL1, Mt-Co3, and Mt-Co1, among others." (PMID 35984745, 2022). "Thus, assessing the exact expression of particular genes, such as mt-ND1, mt-CO1, and mt-ATP6, might serve as a more precious role in determining related clinical outcomes of infection." (PMID 39113822, 2024).
tumor (24 papers, 2012 to 2025). "However, all tumor cells of patient #5 had mutations in MT-CO1 (chrM:7352), while normal epithelial cells from the same patient did not have this mutation." (PMID 35974387, 2022). "Although relatively few studies have investigated MTCO1, its expression has been shown to vary across different tumor types." (PMID 40457691, 2025). "To determine which tumour cell population relied most on high mitochondrial translation levels, we labelled primary tumour sections for the mitochondrial markers MTCO1 and MTCO2." (PMID 35768510, 2022). "The expression of MT-CO1 was reduced in the sliced tumor tissues of the PPCu + NIR 10 min group compared with that in the control group." (PMID 34606010, 2021). "Evaluation of mtDNA content showed that while the original ρ0 cells do not contain any mtDNA, all of the ρ0 tumour-derived cells contain mtDNA and express mtDNA-encoded proteins, exemplified by mtCO1." (PMID 40325182, 2025). "The increased MTCO1 expression in C‐ABL (p = 0.0327) and its specific localization to basal cells suggests a mitochondrial contribution to the metabolic demands of the tumor, particularly in C‐ABL." (PMID 40457691, 2025). "Another study reported the reduced expression of NDUFS4, SDHA, UQCR2, MT-CO1, and ATP5F1A in tumor samples from 94 PCa patients who had undergone radical prostatectomy after tumor diagnosis." (PMID 36901912, 2023). "The gene expressions of AOC1 (P < 0.001), FDX1 (P = 0.003), MT-CO1 (P < 0.001), and ACO1 (P < 0.001) in HCC tumor tissues were remarkably lower than those in normal tissues." (PMID 36313717, 2022). "In the present study, the levels of SDHA, UQCRC2, MT-CO1 and ATP5F1A were significantly reduced in the tumor periphery compared to the control tissue." (PMID 31167495, 2019). "However, five genes (MT-CO1, MT-CYB, MT-DLOOP1, MT-ND1 and MT-ND5) not only presented germline variants, but also different somatic variants exclusive to tumor and internal control groups, indicating a possible association of such genes and variants with tumor development." (PMID 31673122, 2019). "Assessment of fully-assembled respiratory chain complexes by native immunoblot revealed that neutrophils from tumour bearing mice had increased levels of complexes I (NDUFS1) and IV (MTCO1), and significantly increased complex IV activity by in gel activity assay." (PMID 30504842, 2018).
cancer (21 papers, 2008 to 2025). A tumor composed of atypical neoplastic, often pleomorphic cells that invade other tissues. "Irradiated GDC0941 and COMP-treated GDC0941 and COMP-treated cells exhibited lower protein expression of ABCC3, a protein involved in treatment resistance in NSCLC and other cancers, and MT-CO1, a mitochondrial protein associated with cancer progression." (PMID 40141111, 2025). "This process, in turn, promotes cancer stemness and cisplatin resistance by enhancing the MTCO1/OXPHOS axis." (PMID 39656941, 2025). "The mutations at the binding sites of TACO1‐circFOXK2‐HSP90β disturb the ternary complex and inhibit cancer stemness and cisplatin resistance in BCa cells by suppressing the MTCO1/OXPHOS/mtROS axis." (PMID 39656941, 2025). "Consequently, disrupting the TACO1‐circFOXK2‐HSP90β complex inhibits cancer stemness and cisplatin resistance in BCa cells by suppressing the MTCO1/OXPHOS/mtROS axis." (PMID 39656941, 2025). "Another recent report using TaqMan detecting DNAs of human and murine mitochondrial cytochrome c oxidase subunit I (MTCO1) gene was found to determine if human cancer cells were contaminated by murine cells with a sensitivity of 100 murine cells/1 million cancer cells." (PMID 36865791, 2023). "Also among the upregulated genes were mitochondrial protein coding genes (MT-ND3, MT-ND4L, MT-ND4, MT-ND2, MT-CYB, MT-ND1, MT-CO1 etc), which may be as a result of the elevated metabolism characteristic of cancer cells to sustain their survival." (PMID 29132323, 2017). "Mechanistically, mitochondrial TACO1 enhances the translation of the mitochondrial cytochrome c oxidase I (MTCO1), promoting mitochondrial reactive oxygen species (mtROS) by upregulating OXPHOS, consequently driving cancer stemness and cisplatin resistance." (PMID 39656941, 2025). "In addition, six transcripts (MT-ATP6, MT-CO1, MT-CYB, MT-ND1, MT-ND6, and MT-RNR1) were quantified in 62 cancer tissues by real-time RT-PCR." (PMID 18842121, 2008). "Similarly, overexpression of circFOXK2‐WT could increase MTCO1 expression, complex IV activity, OCR, mtROS, cancer stemness, cisplatin resistance, and SOX2 expression levels in T24‐CIS cells, but circFOXK2‐MUT could not." (PMID 39656941, 2025).
neurodegenerative disease (3 papers, 2015 to 2021). A disorder of the central nervous system characterized by gradual and progressive loss of neural tissue and neurologic function. "Mutation in the human MT-CO1 gene has been associated with several diseases, including neurodegenerative disease." (PMID 26225554, 2015). "Here, we found that the species of Mn can increase or arrest the expression of genes such as MT-CO1, MT-CYB, MT-ND4, and COX4I2, which are associated with glycolysis and glycogenesis, and oxidative phosphorylation, along with neurodegenerative diseases such as AD, HD, and PD." (PMID 34941782, 2021).
cardiac diseases (2 papers, 2022). "In addition, two families with HCM had mutations in mitochondrial genes MT-CO1 and MT-ND6; both previously implicated in heart disease, although heteroplasmy proportions are yet to be determined in multiple tissue samples." (PMID 36357925, 2022).
myopathy (2 papers, 2021). A disease of the muscle in which the muscle fibers do not function properly. "Several mutations have been identified in MT-CO1 subunit, including microdeletions and nonsense mutations, which have been associated with the onset of motor neuron disease, multisystem mitochondrial disorders, and myopathy." (PMID 34827632, 2021). "The missense mutation m.G6955A has been detected in the MT-CO1 gene of patients with myopathy." (PMID 34827632, 2021).
adenocarcinoma (1 paper, 2017). A common cancer characterized by the presence of malignant glandular cells. "MCT1, MCT4 and mitochondrial cytochrome c oxidase (MTCO1) expression were determined with immunohistochemistry in esophageal specimens from 129 patients with columnar dysplasia or adenocarcinoma." (PMID 28206968, 2017). "Adenocarcinoma showed slightly higher cytoplasmic expression of MCT1, MCT4 and MTCO1 compared to dysplastic lesions." (PMID 28206968, 2017).
mitochondrial disease (1 paper, 2014). "Notably, deficiencies in MTCO1 expression are often associated with mitochondrial DNA damage and development of mitochondrial diseases." (PMID 25222487, 2014).
MT-CO1 also shares sentences with these, for which no sentence is quoted: malaria (5 papers); Leber hereditary optic neuropathy (3); Leigh syndrome (3); melanoma (3); osteosarcoma (3); Parkinsonism (3); acquired idiopathic sideroblastic anaemia (2); acute kidney injury (2); Anxiety (2); Ataxia (2); breast carcinoma (2); cardiomyopathy (2); cardiovascular disease (2); colorectal cancer (2); deafness (2); head and neck cancer (2); heart failure (2); Huntington disease (2); neuroblastoma (2); Alpers syndrome (1); amyloidosis (1); anaphylaxis (1); angioedema (1); bladder cancers (1); brain ischemia (1); breast tumors (1); carcinosarcoma (1); cardiac hypertrophy (1); chronic kidney disease (1); co-infection (1).
A further 39 diseases each share a sentence with MT-CO1 in 1 paper.